CGB1 (chorionic gonadotropin subunit beta 1)
Tractability: Antibody: UniProt places it where antibodies can reach, with medium confidence; UniProt predicts a signal peptide or a membrane-spanning region; its Gene Ontology location is reachable by antibodies, with medium confidence.
Gene: Protein-coding gene on chromosome 19 (49,035,569 to 49,036,895, reverse strand). Ensembl gene ENSG00000267631.
Subcellular location: Secreted
Gene Ontology:
Molecular function: hormone activity
Biological process: G protein-coupled receptor signaling pathway; cell communication; signaling
Cellular component: extracellular region
Genetic constraint (gnomAD): Loss-of-function variants: 3 observed, 4.84 expected, observed/expected ratio (o/e) 0.62, 90% interval 0.28 to 1.53. That is too few expected variants to judge how well the gene tolerates losing a copy. Missense variants: 126 observed, 149.12 expected, observed/expected ratio (o/e) 0.84, 90% interval 0.73 to 0.98. Synonymous variants: 66 observed, 70.34 expected, observed/expected ratio (o/e) 0.94, 90% interval 0.77 to 1.15.
Homologues: Orthologues: macaque CGB8 (81% identical), Drosophila melanogaster Gpb5 (16% identical). Paralogues in human: CGB2 (99% identical), CGB3 (98% identical), CGB5 (98% identical), CGB8 (98% identical), CGB7 (96% identical), LHB (72% identical), TSHB (32% identical), FSHB (26% identical), GPHB5 (22% identical).
Diseases named in the same sentence as CGB1 in open-access papers:
CGB1 is named in the same sentence as 16 diseases in open-access papers, as found by Europe PMC text mining. Sharing a sentence is not in itself a finding about the gene and the disease. The quoted sentences say what the papers report.
ovarian carcinoma (2 papers, 2013 to 2019). A malignant neoplasm originating from the surface ovarian epithelium. "CGB1 and CGB2 genes were detected to be transcriptionally active only in 20% of tested ovarian cancer tissues and at the lowest level across all tested CGB genes of the cluster." (PMID 31362717, 2019). "Presence of mRNA arising from CGB1 and CGB2 genes appears to be a unique feature of a subset of ovarian cancers." (PMID 31362717, 2019). "Guided by this information, we decided to analyse the activity of CGB1 and CGB2 in ovarian cancer tissues in order to compare their expression pattern with normal ovaries lacking cancerous changes and CG-producing placentas." (PMID 23774837, 2013). "Furthermore presence of mRNA arising from CGB1 and CGB2 genes appears to be a unique feature of a subset of ovarian cancers." (PMID 31362717, 2019). "In fact we previously demonstrated the presence of CGB1 and CGB2 transcripts in ovarian carcinomas." (PMID 31362717, 2019). "Our study demonstrates the presence of CGB1 and CGB2 transcripts in ovarian carcinomas." (PMID 23774837, 2013). "Notably transcription of CGB1 and CGB2 was detected in 20% of ovarian cancer samples." (PMID 31362717, 2019).
ovarian tumours (1 paper, 2019). "In the case of CGB1 and CGB2 gene transcripts, RT-qPCR assay showed that more than 20% of analyzed ovarian tumours expressed CGB1–2, but none of the control ovarian tissues contained detectable levels of these genes transcripts." (PMID 31362717, 2019).
uterine corpus endometrial carcinoma (1 paper, 2020). A endometrial carcinoma (disease) that involves the body of uterus. "In the case of the CGB1 gene, such a difference was recognized for uterine corpus endometrial carcinoma only." (PMID 32957442, 2020).
cancer (1 paper, 2020). A tumor composed of atypical neoplastic, often pleomorphic cells that invade other tissues. "Despite the fact that the studied genes’ expression levels in cancer tissues were low, with the median often equaling zero, the transcriptional activity of the CGB1 and CGB2 genes in cancerous tissues of different origin was confirmed." (PMID 32957442, 2020). "The highest median values of CGB1 expression were noted for two cancers: PAAD and UCEC (median: 0.078 and 0.317, respectively)." (PMID 32957442, 2020). "First, the screening of TCGA transcriptome data related to CGB1 and CGB2 gene expression in different cancers was performed." (PMID 32957442, 2020). "In order to verify the transcriptional activity of CGB1 and CGB2 genes in cancer, we analyzed data collected in TCGA." (PMID 32957442, 2020). "It was also demonstrated that specific targeting of CGB1 and CGB2 with siRNA was much more effective in reducing cancer cell numbers than silencing other CGB genes." (PMID 32957442, 2020). "Since the transcriptional activity of CGB1 and CGB2 in cancer was mainly shown in cell lines, the aim of the present study was to demonstrate the expression of these genes in human cancer tissues of different origin." (PMID 32957442, 2020). "In the same manner, CGB1 and CGB2 may promote the pregnancy-like invasion of cancer cells into specific microenvironments, and later tumor growth and metastasis." (PMID 32957442, 2020).
infection (1 paper, 2008). The state of being infected such as from the introduction of a foreign agent such as serum, vaccine, antigenic substance or organism. "Deletion of the M. grisea Gβ subunit, mgb1, and Cochliobolus heterostrophus CGB1 leads to defective appressorium formation that prevents host penetration and infection." (PMID 18227243, 2008).
tumor (1 paper, 2020). "The expression level of CGB1 in primary tumor and healthy tissue differed for UCEC only (p = 0.0044)." (PMID 32957442, 2020). "Further studies are needed in order to verify the hypothesis that CGB1 and CGB2 genes are involved in tumor growth, invasion and metastasis." (PMID 32957442, 2020).
CGB1 also shares sentences with these, for which no sentence is quoted: Bladder urothelial carcinoma (1 paper); cervical squamous cell carcinoma (1); Esophageal carcinoma (1); head and neck squamous cell carcinoma (1); lung squamous cell carcinoma (1); ovarian serous cystadenocarcinoma (1); pancreatic adenocarcinoma (1); Testis germ cell tumors (1); thymoma (1); uterine carcinosarcoma (1).